TNF (tumor necrosis factor)
Diseases named in the same sentence as TNF in open-access papers (continued):
Sharing a sentence is not in itself a finding about the gene and the disease.
pancreatic cancer (continued). "Previous studies have not yet investigated the relationship between SLC22B5 and critical biological processes, including EMT, TNF-α signaling, or angiogenesis, in pancreatic cancer." (PMID 40282424, 2025). "OAd-TNF-α-IL2 delivers the pro-T-cell cytokines IL-2 and TNF-α in the immunosuppressive TME of pancreatic cancer, and enhances the antitumor efficacy of mesothelin-CAR T-cell therapy." (PMID 40148310, 2025). "CC-3 increased the secretion of IL-2, IFN-γ, IL-10, and TNF, stimulated the proliferation of effector memory and central memory T cells in the presence of B7-H3-positive cells, and significantly destroyed pancreatic cancer cells." (PMID 40214484, 2025). "Supporting our results, targeting TNF-α-producing macrophages in pancreatic cancer can induce antitumor immunity." (PMID 40316021, 2025). "Co-culture significantly increased PDAC cell migration, indicating that a macrophage-TNF inflammatory environment promotes pancreatic cancer cell migration." (PMID 40634284, 2025). "In this model, pancreatic tumor cells release TNF-α and IL-1β proinflammatory cytokines, which had been previously reported, stimulating CAFs to secrete TSLP." (PMID 40453074, 2025). "Another research shows that TNF from neutrophils can result in immune suppression and therapy resistance in pancreatic cancer." (PMID 40313883, 2025). "For example, blocking TNF with antibodies in mice inhibited pancreatic tumor growth and metastasis and showed promise in treating human PDAC xenografts." (PMID 39178856, 2024). "Per1 mediates tumor necrosis factor-α (TNF-α) to inhibit the proliferation of human pancreatic cancer cells (MIA PaCa-2)." (PMID 39012661, 2024). "Their results showed that the CAR-T cells expressed high levels of the CAR on their surface and secreted high levels of IFN-γ and TNF-α upon stimulation with CEA-positive pancreatic cancer cell lines." (PMID 39417449, 2024). "TNK1 has been observed to promote apoptosis induced by the tumor necrosis factor alpha and its activity has been shown to stimulate growth and survival of pancreatic cancer cells." (PMID 39446839, 2024). "Another phase II trial combined thalidomide with capecitabine in advanced or metastatic pancreatic cancer patients, inhibiting TNF mRNA stability and TNF production." (PMID 39195299, 2024). "Inflammatory cytokines like TNF-α, IL-1β and IL-6 were estimated in the spinal tissue of 5HT2A antagonist treated pancreatic cancer mice." (PMID 38629654, 2024). "Their study found that the CAR-T cells expressed high levels of CAR on their surface and secreted high levels of IFN-γ and TNF-α upon stimulation with MSLN-positive pancreatic cancer cell lines." (PMID 39417449, 2024). "Previous studies have reported that MA significantly enhances tumor necrosis factor-α-induced inhibition of pancreatic cancer cell proliferation by suppressing cyclin D1, COX-2, and c-Myc expression levels." (PMID 39624845, 2024). "Localized STING agonist administration have been previously shown to cause intratumoral hemorrhagic necrosis in a murine model of pancreatic cancer, which was associated with STING-mediated induction of TNF-α." (PMID 37465665, 2023). "An additional risk model PRG based on more immune-related genes (CASP4, GSDMC, IL-18, NLRP1, NLRP2, PLCG1, TIRAP, and TNF) was developed, which can be used to predict pancreatic cancer prognosis with an accuracy of medium to high." (PMID 37893166, 2023). "The growth of BxPc3 and COLO 357 pancreatic cancer cells similarly reduced by TNF-α, but it also strongly enhances their invasive properties." (PMID 37185713, 2023). "TNF-α enhances the invasiveness of pancreatic cancer cells in vitro and promotes tumour growth and metastasis in mouse models of orthotopic pancreatic cancer." (PMID 37686338, 2023). "Recent evidence has shown that signaling pathways, including tumor necrosis factor (TNF) and hypoxia-inducible factor-1 (HIF-1), are associated with EMT in pancreatic cancer." (PMID 36831572, 2023).
pancreatic cancer (continued). "These research findings indicate that VRK2 activates the TNFα signaling pathway in pancreatic cancer cells." (PMID 35173553, 2022). "Our results showed that the phosphorylation levels of IKKα/β, NF-κB, p65, IkBα, p38, JNK and ERK increased in a time-dependent manner after TNF-α (10 min and 30 min) stimulation in pancreatic cancer cells (MIA PaCa-2)." (PMID 35541911, 2022). "We further revealed that alizarin triggered pancreatic tumor cell apoptosis by inhibiting nuclear translocation and weakening the activity of NF-κB after TNF-α stimulation." (PMID 35541911, 2022). "Enhancement of the muscarinic signaling pathway in pancreatic cancer has been shown to directly inhibit tumor stem cells, CD11b+myeloid cells, TNFα levels, and hepatic metastatic growth through CHRM1." (PMID 35295188, 2022). "The NF-κB signaling pathway activated by TNFα plays a rather important role in the initiation and progression of pancreatic cancer." (PMID 35173553, 2022). "DCs downregulate TLR4, TNF-α, and IL-12 expression upon treatment with miR-203-rich exosomes derived from pancreatic cancer cells, which prevent DC-driven antigen presentation." (PMID 35501802, 2022). "TQ inhibits these factors from exerting biological effects by inhibiting the activation of inflammatory factors mediated by NF-κB and TNF-α as well as their transport from the cytoplasm to the nucleus in pancreatic cancer cells." (PMID 36686732, 2022). "Compared to the supernatant from cultured normal pancreatic cells which did not activate previously trained macrophages, the supernatant from cultured KPC and Pan02 pancreatic cancer cells stimulated more TNF-α production in β-glucan trained macrophages." (PMID 35140221, 2022). "In another study, a functional–genomic screening revealed that autophagy enabled pancreatic cancer cells to evade CD8+ T cell killing via Tumor Necrosis Factor-alpha (TNFα)-induced cell death." (PMID 35159234, 2022). "Two clinical trials in the USA evaluated the effects of TNF-α and TNF-α inhibitors in patients with pancreatic cancer." (PMID 35493517, 2022). "Another study showed that proliferating T cells produced less IFN-γ and TNF-α when fibroblast cells were present in pancreatic cancer, thus contributing to diminished immune function." (PMID 36474268, 2022). "The results show that after TNF-α stimulated pancreatic cancer cells, the cytoplasmic p65 was decreased and the nuclear p65 expression was increased significantly." (PMID 35541911, 2022). "The CAC-associated pro-inflammatory cytokines, TNF-α and IL-6 and CCM from PANC-1 human pancreatic cancer cells promoted lipolysis in mature 3T3-L1 adipocytes as judged by an increase in glycerol release and free fatty acids (FFA)." (PMID 35684106, 2022). "The anti-TNFR1 antibodies did not affect the level of the PD-L1 protein in TNF-α-treated KPC cells, whereas the addition of anti-TNFR2 antibodies abolished the TNF-α-induced upregulation of PD-L1 expression in pancreatic cancer cells." (PMID 35260434, 2022). "Some cytokines in tumor microenvironment, such as TNF-α, played an optimal role in the pathogenesis of malnutrition in pancreatic cancer." (PMID 36157419, 2022). "Levels of TNFα in the spleen and circulation were suppressed by bethanechol in a mouse model of pancreatic cancer." (PMID 35295188, 2022). "The strong anti-inflammatory effects of TQ on NF-κB, TNF-α, and other inflammatory mediators highlight its potential as a preventive and therapeutic strategy for pancreatic cancer." (PMID 36686732, 2022). "Of the 14 pancreatic cancer patients carrying the mutant TNF-α 308G/A (rs1800629) gene, 10 patients were cachectic (15%), and four patients were non-cachectic (5%), showing a significant positive association between TNF-α 308G/A gene mutation and cachexia." (PMID 34900737, 2021). "The anti-tumor effects of DC/cytokine-induced killer cells against pancreatic cancer was evaluated by proliferation and killing rates and TNF-α and perforin secretion." (PMID 33435564, 2021).
pancreatic cancer (continued). "Bladder cancer, pancreatic cancer, the TNF signaling pathway, and the PI3K–Akt signaling pathway are all reportedly related to diarrhea." (PMID 34671661, 2021). "Pancreatic cancer cell-derived exosomes inhibited immune response via miR-203 and thus downregulated Toll-like receptors, and downstream cytokines such as tumor necrosis factor-alpha (TNF-α) and IL-12 in dendritic cells (DC)." (PMID 34677212, 2021). "Similar findings were observed in pancreatic cancer, where TNFα was the macrophage-secreted cytokine responsible for upregulation of PD-L1 in pancreatic ductal adenocarcinoma cells." (PMID 33540543, 2021). "Since we observed that MLK3 and MAP4K4 are overexpressed in pancreatic cell lines and tumors, and TNFα (a common agonist) can promote pancreatic cancer, we planned to elucidate the functions of the MAP4K4-MLK3 axis in pancreatic cancer models." (PMID 34511598, 2021). "Clinical studies have shown that pancreatic cancer patients have higher serum levels of TNF-α in comparison with normal subjects." (PMID 33730072, 2021). "We show that in vivo administration of TNF-α strongly increases the formation of CAFs and an abundant desmoplastic stroma in pancreatic tumours." (PMID 34172716, 2021). "Anti-TNFα antibody therapy has been demonstrated to exhibit robust anti-tumor effects in mouse models of pancreatic cancer and achieve disease stabilization in individuals with diagnoses of metastatic breast and recurrent ovarian cancer." (PMID 34650923, 2021). "The main pathways of the relevant targets in PSD were as follows: hepatitis B (hsa05161), pathways in cancer (hsa05200), pancreatic cancer (hsa05212), bladder cancer (hsa05219), and the TNF signaling pathway (hsa04668)." (PMID 34471414, 2021). "Exogenous TNFα (20ng/mL) promoted R211 pancreatic cancer cell migration and PI3Kα inhibition by BYL‐719 inhibited cell migration induced by TNF‐α." (PMID 34033220, 2021). "In particular, TNF-α potently induces pancreatic cancer metastasis in a mouse model which can be effectively inhibited by infliximab or etanercept (TNF-α inhibitors)." (PMID 35056961, 2021). "Further, TNF-α or TRAIL signaling also play important roles in the induction of PICs as well as TAPs as has been reported for pancreatic tumor cells in an NFκB-dependent manner." (PMID 34771621, 2021). "TNF-α has been shown to increase the antitumor activity of gemcitabine in pancreatic cancer; however, its curative effect does not seem to be perfect due to the activation of the NF-κB signaling pathway." (PMID 34276760, 2021). "In pancreatic cancer, blocking TNFα strategies proved to be effective in animal models and in patients." (PMID 33540543, 2021). "One of the main pro-inflammatory cytokine expressed by obese adipose tissue is TNF-α, which was demonstrated to play a significant role in pancreatic tumor promotion and invasion." (PMID 32659999, 2020). "High levels of cytokines IL-1β, IL-6, IL-8, IL-10, TGF-β, and TNF-α are observed in patients with pancreatic cancer compared to healthy patients." (PMID 32174830, 2020). "This screening was carried out in human pancreatic cancer Panc-1 cells, which are known to be sensitive to TNF-α/Smac mimetic." (PMID 32411707, 2020). "In our study, we evaluated the changes in several important pro-inflammatory cytokines in pancreatic cancer, including TNF-α, IL-6, and IL-1β." (PMID 33634030, 2020). "Two clinical trials conducted in the United States evaluated the effects of TNFα and of TNFα inhibitors in patients with advanced pancreatic cancer." (PMID 30764482, 2019). "Due to the described evidence of TNF-α implication in pancreatic cancer progression, Egberts and his group investigated the effects of the chimeric monoclonal antibodies infliximab and etanercept on PDAC cells in both in vitro and in vivo models." (PMID 31191652, 2019).
pancreatic cancer (continued). "The increased invasiveness of pancreatic cancer cells following TNFα treatment is also correlated with stemness and increased expression of the epidermal growth factor (EGF) receptor, these TNFα effects being potentiated by TGFβ." (PMID 30764482, 2019). "In contrast to in vivo or in vitro DMXAA-treated DCs and macrophages, pancreatic cancer epithelial cells produced little if any TNFα, VEGF or IL-1α." (PMID 31036082, 2019). "In the PDAC setting, it has been shown that not only immune cells, but also human pancreatic tumor cells, can produce and secrete TNFα at picogram levels." (PMID 30764482, 2019). "Similar to NM, GM exerted significant antitumorigenic effects on suppression of TNF-α-induced NF-κB expression and promotion of caspase-3, 7 activity in human pancreatic cancer cells." (PMID 31552177, 2019). "Consistent with this evidence, TNF-α levels are high in patients affected by pancreatic cancer and correlate with advanced status of the neoplasia." (PMID 31191652, 2019). "TNFα is also relevant to liver metastasis formation as, in the setting of both colorectal and pancreatic cancer, TNFα blockade reduced metastatic outgrowth." (PMID 31064120, 2019). "Another study of pancreatic cancer provided evidence for HH/GLI activation in response to inflammatory TNF and IL1 signaling." (PMID 31878932, 2019). "In conclusion, rfhSP-D upregulates pro-apoptotic factors such as TNF-α, NF-κB, and Fas to activate caspase cascade to induce apoptosis in pancreatic cancer cell lines, which needs further exploration in orthotropic murine models." (PMID 29915574, 2018). "In particular, in pancreatic cancer cells, Sirt6 induces the expression of proinflammatory cyto-/chemokines [interleukin 8 and tumor necrosis factor α (TNFα)]." (PMID 29535637, 2018). "PPARγ repression in pancreatic cancer cells results in the constitutive production of pro-inflammatory cytokines, including TNFα, IL-6, and IL-1β, relevant in the recruitment of macrophages and neutrophils into the tumor site." (PMID 30154786, 2018). "The pro-inflammatory and immunomodulatory effect of TNFα is at the basis of its pro-tumor activity, observed in different malignancies including cutaneous, ovarian, pancreatic cancer, and tumors of the pleural cavity and the bowel." (PMID 30154786, 2018). "In vitro TNFα significantly stimulated growth (p < 0.05) and migration (p < 0.05) of pancreatic cancer cells." (PMID 28160574, 2017). "Astonishingly, the stimulation of the murine pancreatic cancer cell line 6606PDA with TNFα led to an enhanced proliferation and migration of this cell line." (PMID 28160574, 2017). "We investigated the roles of HIF-1α and HIF-2α in cancer cell death induced by tumor necrosis factor (TNF)-related apoptosis-inducing ligand (TRAIL) using human pancreatic cancer cell lines." (PMID 28476028, 2017). "Stimulation of pancreatic tumor cells with different concentrations of TNFα resulted in a significant increase of migration of cells into the scratch (p < 0.0001)." (PMID 28160574, 2017). "Vagotomy can increase tumor growth and worsen survival in a murine pancreatic cancer model mediated through TAMs and TNFα." (PMID 28160574, 2017). "The results suggest that pancreatic cancer cells are similar with normal pancreatic cells with the same changing trend for the expression of NF-κB, TNF-α, SIRT1, and LC3 II after picroside II treatment." (PMID 28713490, 2017). "This study analyses the effects of vagotomy on tumor growth and survival in a murine, pancreatic cancer model in wild-type and TNFα-knockout (−/−) mice." (PMID 28160574, 2017). "Serum TNF-α concentration was significantly higher in the cholangiocellular carcinoma and pancreatic cancer groups compared to other groups." (PMID 29410961, 2017). "TNF-α promotes the invasiveness of human pancreatic cancer cells and promotes tumor growth and metastasis in mice." (PMID 28578701, 2017).
pancreatic cancer (continued). "In this study we investigated how the destroyed mechanism of neural inhibition following vagotomy affected tumor-growth of pancreatic cancer in vivo using a murine syngeneic orthotopic model, thereby shedding light onto the role of TNFα in pancreas cancer." (PMID 28160574, 2017). "Pancreatic tumor cells also release the pro-inflammatory cytokines IL-1β and TNF-α, which play a critical role in the malignancy of pancreatic ductal adenocarcinoma (PDA)." (PMID 29245934, 2017). "Another example of TNF-induced Notch activation is observed in a mouse pancreatic cancer model where TNF promotes expression of Notch target genes Hes1 and Hey1." (PMID 26936847, 2016). "Again, TNF-α independently and significantly predicted outcomes in all pancreatic cancer cases as well as PDAC cases (HR = 1.735, 95% CI: 1.046-2.877, P = 0.0327; HR = 1.868, 95% CI: 1.097–3.183, P = 0.0214, respectively)." (PMID 27835602, 2016). "In all pancreatic cancer cases, median OS of high TNF-α expression subgroup was 10 months (95% CI, 7.96–12.04), while the low TNF-α expression subgroup had a median OS of 12 months (95% CI, 3.22–20.78)." (PMID 27835602, 2016). "In one murine study, the presence of TNFα and IL-17-producing CD4+ T cells in pancreatic cancer was associated with relatively aggressive disease." (PMID 27777771, 2016). "SIRT6 promoted pancreatic cancer cell migration by inducing cytokines such as interleukin-8 and tumor necrosis factor in a Ca2+-dependent manner." (PMID 27777384, 2016). "Dammarane triterpenoid 1, isolated from Borassus flabellifer seed coat, inhibits tumor necrosis factor-α and showed good antiproliferative activity against pancreatic cancer cell line." (PMID 27382642, 2016). "Results of multivariate regression model further strengthen the prognostic values of TNF-α expression, as it was identified as an independent prognostic marker of pancreatic cancer." (PMID 27835602, 2016). "Kaplan-Meier analysis and the log-rank test showed that high expression of TNF-α in both all pancreatic cancer cases and PDAC cases predicted poor survival (P = 0.0061 and 0.013, respectively)." (PMID 27835602, 2016). "Among all the 100 pancreatic cancer cases, 58 (58%) cases were TNF-α high expression and 42 (%) cases were low expression." (PMID 27835602, 2016). "Our further analysis of TNF-α expression in pancreatic cancer patients indicated that high TNF-α expression predicted poor survival." (PMID 27835602, 2016). "In contrast, treatment with TNF (43 ng/ml) and actinomycin D (ActD; 1 μg/ml), a combination known to induce apoptotic cell death in pancreatic cancer cells, resulted in TX-insensitive cell death, demonstrating pathway specificity." (PMID 26097885, 2015). "For instance, a recent murine experimental model has demonstrated that IFN-γ and TNF-α produced by Th1 cells are capable of inducing prolonged senescence in pancreatic tumors, by inducing expression of the transcription factors JUNB and INK4A." (PMID 24672527, 2014). "We found that there were higher levels of IL-6, IL-8, IL-10 and TNFα in patients with pancreatic cancer compared to healthy controls (for all, at least p<0.03)." (PMID 24849506, 2014). "In order to further understand the functional status of NK cells following exposure to pancreatic cancer cells, the concentrations of cytokines (GM-CSF, TNF-α and IFN-γ) in the supernatants following cell culture were determined by ELISA." (PMID 25274283, 2014). "Overexpression of the MSLN gene was shown to enhance interleukin (IL)-6 signaling, and to confer resistance to tumor necrosis factor (TNF)-α mediated apoptosis in pancreatic cancer cell lines." (PMID 25118887, 2014). "A study of pancreatic cancer patients demonstrated that tumor-produced cytokines (TNF and IL-1β) triggered activation of a Th2 phenotype in cancer-associated fibroblasts, dendritic cells, and naïve CD4+ T cells." (PMID 24672527, 2014).